PDK4 (pyruvate dehydrogenase kinase 4)
Diseases named in the same sentence as PDK4 in open-access papers (continued):
Sharing a sentence is not in itself a finding about the gene and the disease.
cancer (continued). "Most of the validated genes, such as IL15, ITGAM, PDK4, and IRX5, have been implicated in AML progression and/or as survival predictors in several types of cancers." (PMID 31740623, 2019). "Microarray revealed that the reduced expression of FAM210B in cancer cells also showed a lower expression of PDK4." (PMID 28594398, 2017). "The basal and maximum OCR were partially reversed by restoring PDK4 gene expression in siFAM210B pooled cancer cells." (PMID 28594398, 2017). "To address the effects of the alteration of oxidative phosphorylation (OXPHOS) activity on the metastasis potential, we tested the roles of PDK4 knockdown or the mitochondrial complex I inhibitor, rotenone, on cancer cell invasion." (PMID 28594398, 2017). "On the other hand, PDK4 restoration or blockade of mitochondrial respiration in FAM210B knockdown cancer cells partially reversed their invasive potential." (PMID 28594398, 2017). "The consequences of PDK4 expression on cancer progression and response to therapy are likely to be context dependent." (PMID 26576332, 2015). "To explore PDK4 expression levels in a broad range of cancer types, we surveyed Gene Logic microarray data covering multiple types of human tumor biopsies and normal tissues." (PMID 25379179, 2014). "In addition, the IGF2BP3 and YTHDF1/eEF-2 complexes increase PDK4 mRNA stability through the m6A modification system, a process that promotes the glycolytic process of cancer cells and accelerates CC development." (PMID 40356909, 2025). "Furthermore, METTL3 facilitates the m6A modification of pyruvate dehydrogenase kinase 4 (PDK4), increases PDK4 mRNA translation, stimulates cancer cell glycolysis, and subsequently promotes the growth and progression of CC." (PMID 40356909, 2025). "Notably, PPARD was reported to bind PPREs in the promoters of ANGPTL4 and PDK4 in cancer cells, leading to their upregulation." (PMID 40652248, 2025). "PDK4, one from the PDKs family, could be widely involved in various cancers, including migration, invasion, apoptosis, and transformation." (PMID 40242460, 2025). "Among these genes, PDK4 regulates glucose metabolism by inhibiting pyruvate dehydrogenase complex and promotes glycolytic metabolism in tumor cells, an altered metabolism that is a typical feature of cancer cells." (PMID 39650664, 2024). "During the aerobic glycolysis of cancer cells, Pyruvate dehydrogenase kinase 4 (PDK4) is one of the most important factors which can direct carbon flux into glycolysis from oxidative phosphorylation (OXPHOS) and HK2 (hexokinase 2) is a key rate-limiting enzyme in aerobic glycolysis." (PMID 38343637, 2024). "APOD, ACTA2, PDK4 and SAPCD2 have all been linked to the development of cancer in several studies." (PMID 38436027, 2024). "PDK4 positively regulates glycolysis in some tissues and cancers." (PMID 38554157, 2024). "Similarly, previous studies indicated that targeted demethylation of PDK4 suppresses glycolysis, while m6A sites of HRas proto-oncogene, GTPase targeted by the dm6ACRISPR system can decrease cancer proliferation and metastasis." (PMID 39059495, 2024). "Therefore, CCL20, FBL, and PDK4 emerged as common biomarkers for IS and pan-cancer, crucial for predicting prognosis in patients with both conditions." (PMID 38914792, 2024). "In cancer, PDK4 is a key enzyme in aerobic glycolysis and mitochondrial oxidative reactions." (PMID 38671369, 2024). "Numerous studies have shown the discovery of anoikis as an important mechanism for cancer invasion and metastasis in gastric, breast, prostate and lung cancers; for example, upregulation of the PDK4 gene leads to chemoresistance in LC and promotes cancer cell proliferation." (PMID 38319706, 2024). "Moreover, PDK4 protein level was higher only in CAAT of normal-weight women with malignant tumors compared to CAAT of normal-weight women with benign tumors." (PMID 38247846, 2024).
cancer (continued). "We hereby conclude that the resistance-minimizing effects of PDK4-targeting strategy are not limited to a specific cancer type, but may have implications to a wide range of malignancies." (PMID 37903887, 2023). "Epigenetic silencing of PDK4 has also been reported in other cancers." (PMID 36980540, 2023). "However, cancer cells can also evade ferroptosis by utilizing metabolic reprogramming, such as the pyruvate dehydrogenase kinase 4 (PDK4)-mediated inhibition of pyruvate oxidation and fatty-acid synthesis." (PMID 37372148, 2023). "PDK4 has been reported to block a metabolic switch from glycolysis to predominantly fatty acid synthesis and contribute to ferroptosis resistance in certain cancer cells, such as pancreatic ductal adenocarcinoma (PDAC) cells." (PMID 37842240, 2023). "However, the expression of PDK4 in some cancers, which benefit from a high level of OXPHOS activity is down-regulated." (PMID 37863991, 2023). "PDK4-dependent lactate production by senescent stromal cells is shown to promote cancer growth and drug resistance and might have a broader role in the emergence of age-associated diseases." (PMID 37903887, 2023). "Previous studies reported that PDK4 was decreased in different cancer types." (PMID 37296697, 2023). "Together, there is an inherent link between cellular senescence, PDK4 upregulation, lactate production and age-related systemic degeneration, which may culminate during chronic disease development such as cancer progression." (PMID 37903887, 2023). "However, analysis of BCa specimens in TCGA demonstrated a novel trend, as PDK4 expression was suppressed in cancer compared to normal controls." (PMID 36980540, 2023). "Specifically, HTR2B seemed to be the most upregulated in PCa lines upon exposure to PDK4+ stromal cell-derived CM, validating future efforts to determine whether it accounts for a principal force driving malignant changes of recipient cancer cells." (PMID 37903887, 2023). "GO analysis, GSEA, and PPI showed that PDK4 expression may regulate cell adhesion, metal ion transport, synaptic activity, and cancer cell metabolism in GC." (PMID 35626257, 2022). "PDK4 inhibition stimulates the mitochondrial metabolism of pyruvate in cancer cells, which may suppress cancer cell proliferation." (PMID 36362028, 2022). "PDK4 has also been investigated in the occurrence, development, and migration of cancer." (PMID 36358433, 2022). "Moreover, recent studies reported that YTHDF1 was involved not only in the glycolysis of cancer cells by promoting mRNA stability of PDK4 but also in cancer drug resistance." (PMID 34745970, 2021). "Additionally, detachment of some cancer cell lines has been observed to promote upregulation of PDK4, and a subsequent suppression of PDH flux; resulting in a reduced proliferative capacity." (PMID 34283054, 2021). "Studies have shown that m6A regulates the glycolysis of cancer cells through PDK4." (PMID 34220962, 2021). "Nevertheless, the particular mechanism relating to PDK4 in carcinoma still needed to be explored." (PMID 34220962, 2021). "Additionally, PDK4 protein was found in both the nucleus and cytoplasm of HCC cells based on an immunofluorescence (ICC) assay, and PDK4 protein was also found in the nucleus and cytoplasm of cancer cells contained in HCC clinical specimens based on IHC." (PMID 32489458, 2020). "Both high expression of PDK4 and Mettl3 reduced the survival rate of cancer patients." (PMID 32444598, 2020). "It indicated that m6A modification may delay the degradation of mature mRNA of PDK4 in cancer cells." (PMID 32444598, 2020). "Our study reveals that m6A regulates glycolysis of cancer cells through PDK4." (PMID 32444598, 2020). "Our present study reveals that m6A can positively regulate the glycolysis of cancer cells via regulation of pyruvate dehydrogenase kinase 4 (PDK4), one of the most important factors which can direct carbon flux into glycolysis from oxidative phosphorylation (OXPHOS)." (PMID 32444598, 2020).
cancer (continued). "However, PDK4 can act as tumor suppressor in cancers that depend on high OXPHOS activity and/or high amounts of TCA cycle intermediates, as has been shown in PCa." (PMID 33384955, 2020). "For comparison, we likewise assessed the expression of PDK4 within primary cancer sites." (PMID 30808993, 2019). "Collectively, we propose that the EMT program and enhanced migratory and invasive properties may coexist with mitochondrial reprogramming in FAM210B or PDK4 knockdown cancer cells, while the mechanism needs further clarification." (PMID 28594398, 2017). "Although PDK1 and PDK2 have been previously proposed as cancer drug targets, our findings suggest that PDK4 may function as a metabolic tumor suppressor." (PMID 25379179, 2014). "The underlying molecular signaling mechanism may relate in part to the cancer-selective enhancement of PDK4 expression, suggesting that mitochondrial oxidative phosphorylation is important in the energy metabolism of HCC cells." (PMID 24376596, 2013). "PDK4 is usually not highly expressed in PDAC but is associated with cancer cachexia." (PMID 39684873, 2024). "Furthermore, PDK4 protein was observed in both the nucleus and cytoplasm of 7402 and 7404 cells based on an immunofluorescence assay, and PDK4 protein was also detected in the nucleus and cytoplasm of cancer cells contained in HCC clinical tissue specimens based on IHC." (PMID 32489458, 2020). "In addition, an involvement of miR-122 in stem-associated phenotypes was previously reported in HCCs, where it inhibited cancer stem cell (CSC) glycolysis through the direct targeting of PDK4, suggesting that miR-122 is fundamental for metabolic reprogramming of HCC cells." (PMID 30717317, 2019). "Similarly to NSCLC, an interesting in vivo study performed in advanced bladder cancer showed an increased expression of PDK4 isoform in high grade compared to lower-grade cancers and cotreatment of DCA and cisplatin dramatically reduced tumour volumes as compared to either DCA or cisplatin alone." (PMID 31827705, 2019). "The YTHDF1/eEF-2 complex and IGF2BP3 interact with the m6A-modified 5′UTR of pyruvate dehydrogenase kinase 4 (PDK4), promoting its translation, elongation, and mRNA stability, thus increasing the expression of PDK4 and glycolysis of cancer cells." (PMID 40428320, 2025). "Once PDH is inhibited by pyruvate dehydrogenase kinase 4 (PDK4), pyruvate oxidation and the production of fatty acids are blocked, thus hampering ferroptosis and facilitating the development of cancers." (PMID 38459004, 2024). "Interestingly, tumour‐induced alterations in the expression of Atrogin1, MuRF1, Pik3r1, Pdk4, Myh4, Myh2 and Myh1 were attenuated in EDA2R‐deficient muscles, implying that the EDA2R pathway contributes to the reprogramming of muscle gene expression during cancer cachexia." (PMID 39001644, 2024). "While malignant tumor tissue showed lower protein levels of PDH, CS, and PDK4 in both normal-weight and obese women, CAAT showed an increase in the protein levels of the same enzymes with the exception of PDH in normal-weight women." (PMID 38247846, 2024). "Pyruvate dehydrogenase kinase 4 (PDK4), a central regulator of cellular energy metabolism, is highly expressed in various malignant tumors." (PMID 38671369, 2024). "Altogether, this finding highlights that PDK4 and, possibly, all the PDK isoforms represent promising targets for cancer therapy of highly aggressive KRAS mutant cancers." (PMID 36835086, 2023). "The data further implied the potential role of PDK4 as a contributing factor for senescence and the SASP, although cancer cells displayed a SASP induction pattern somehow distinct from their normal stromal counterparts." (PMID 37903887, 2023). "They reported that PDK4 knockdown by specific small interfering (si)RNAs downregulates mutant (KRAS) expression and consequently strongly suppresses the growth of cancer cells." (PMID 36835086, 2023).
cancer (continued). "Data from mice developing BCa carcinomas and treated by doxorubicin (DOX)/PDK4-IN generally phenocopied those in animals with PCa." (PMID 37903887, 2023). "Pyruvate dehydrogenase kinase 4 (PDK4) is involved in m6A regulated glycolysis and ATP production of cancer cells." (PMID 35351856, 2022). "Targeted demethylation of PDK4 mRNA by dm6A-CRISPR reversed METTL3-induced PDK4 expression and lactate production, implying that METTL3 is a driver of aerobic glycolysis in cancer cells." (PMID 36289851, 2022). "CD36, PDK4, and THBS1 were highly expressed in cancer tissues, and G3BP2, PTPRB, and TMEM125 were lowly expressed in cancer tissues." (PMID 36147333, 2022). "In a variety of cancer types, PDK1-3 have been proposed to play oncogenic roles, whereas PDK4 has been proposed to play both oncogenic and tumor suppressive functions depending on the tumor type." (PMID 35692804, 2022). "Those 6 genes in the model (PDK4, MPP1, ASGR1, MS4A14, FCER1A and MX2), rarely reported in cancers, were found to be significantly related to the prognostic survival of KIRC patients." (PMID 34606472, 2021). "It is reported that high PDK4 expression indicates a worse prognosis of OC patients, and PDK4 activates the STAT3/AKT/NF-κB/IL-8 signal pathway to enhance the metastasis and glycolysis of OC cells, and to help cancer cells maintain stemness." (PMID 33926489, 2021). "PDK1, PDK2, PDK3, PDK4, PDP2, and PDPR genes can regulate the glucose metabolism and glycolysis of cancer cells." (PMID 34199666, 2021). "While PDK1 is less sensitive to DCA than PDK2 or PDK4 (PDK2 > PDK4 > PDK1 > PDK3), DCA reduced the abundance of PDK1 in cancer cells and fibroblasts, indicating that inhibition is not the only mechanism by which DCA reduces the PDK1 function." (PMID 34445316, 2021). "In cancer cells, detachment from the ECM leads to increased expression of PDK4, with PDH-mediated suppression of pyruvate metabolism; thus, it is possible that a similar metabolic shift occurs in HSCs." (PMID 32414151, 2020). "The central gene is PIK3R1 in Module 0, which module contains eight DEGs related to classical cancer pathways (FCER1A, GNG11, IGF1, LIFR, PDK4, PIK3R1, RCAN2, and UGCG)." (PMID 31119098, 2019). "Expression of PDK4 is reported to increase upon detachment of cells from the ECM, and its expression can be inhibited by ERK-dependent signaling in cancer cells." (PMID 27462466, 2016). "Combining lactate export inhibition and PDK4 targeting with senolytic drugs may enhance therapeutic efficacy in addressing TIS and improving cancer treatment outcomes." (PMID 40750580, 2025). "Generally, PDK4 and LDHA collaborate to enhance the glycolysis of cancer cells." (PMID 38200513, 2024). "Basically, in line with our in vitro data, upregulated PDK4 was generally localized in stroma, in a sharp contrast to the adjacent cancer epithelium, which had limited or no staining." (PMID 37903887, 2023). "PDK4 collaborates with METTL3 to induce proliferation and hepatic chemosensitivity cancer cells." (PMID 35186927, 2022). "Moreover, the TCGA database showed that PDK4 mRNA levels were upregulated and are correlated with poor survival of GBM and other cancer patients." (PMID 34058053, 2022). "Pyruvate dehydrogenase kinase 4 (PDK4) may promote cancer progression by regulating epithelial-mesenchymal transition (EMT) and cancer cell metabolism." (PMID 32855630, 2020). "Unlike the oncogenic roles of PDK1-3 in multiple human cancers, the findings from this study and those from other labs have illustrated that PDK4 plays a divergent role in various cancers, depending on different cell contexts." (PMID 32489458, 2020). "Conversely, in cancer cells that have undergone tumor progression via epithelial–mesenchymal transition (EMT), a low PDK4‐mediated metabolic shift from glycolysis to OXPHOS was reported, and knockdown of PDK4 was sufficient to induce EMT in human non‐small‐cell lung cancer (NSCLC) cell lines." (PMID 32323921, 2020).
cancer (continued). "Although the current study suggests that FXR activation and the downstream up-regulation of PDK4 can directly promote proliferation of cancer cells, it is important to note that the exact role of FXR and PDK4 in the tumor biology can be complex, and particularly, in the in vivo settings." (PMID 26728993, 2016). "In addition, it has been reported that in the cancer-related senescence microenvironment, SASP factors induce PDK4 expression in tumor stromal cells and thereby metabolic restructuring promotes lactate production, suggesting that SASP activates PDK4." (PMID 40623060, 2025). "As current research indicates that ATP production is not the likely limiting factor for cancer proliferation, the action of PDK4 on metabolism may ultimately reduce metabolic intermediates necessary for proliferation." (PMID 36980540, 2023). "To substantiate PDK4 inducibility in vivo, we profiled a subset of patients with PCa whose pre- and post-chemotherapy biospecimens were both accessible, and found notably upregulated PDK4 in stroma, but not cancer epithelium, of each individual post-chemotherapy." (PMID 37903887, 2023). "In this study, there was a negative regulation between the PDK4 expression and CA content, proving that the TCA cycle might be down-regulated under hypoxia, and reducing the TCA cycle in cancer cells to reduce oxygen consumption is also an important regulatory strategy of adapting to hypoxia." (PMID 35268153, 2022). "Furthermore, our results suggested that EGFR degradation was attributed to Erk inactivation-induced PDK4 up-regulation to decrease ATP and activate AMPK, providing the clue that AMPK activation might enhance anti-cancer of dasatinib through targeting EGFR." (PMID 24457597, 2014). "The results of the present study suggest that ACR may suppress the enhanced energy metabolism of JHH7 cells but not Hc cells; this occurs at least in part via the cancer-selective enhancement of PDK4 expression." (PMID 24376596, 2013). "Although multiple studies reported the use of DCA (but not PDK4‐IN‐1 hydrochloride or VER‐246608) in humans, particularly in the treatment of cancer, without affecting normal cells, we wanted to determine the vulnerability of human astrocytes." (PMID 34058053, 2022). "The gene expression profile coincides with the metabolic alterations, hinting to a critical role of PDK4 and PHGDH in mediating the metabolic reprogramming and proliferative effects of FXR activation in cancer cell lines but not the primary hepatocytes." (PMID 26728993, 2016).